HIF1A (hypoxia inducible factor 1 subunit alpha)
Diseases named in the same sentence as HIF1A in open-access papers (continued):
Sharing a sentence is not in itself a finding about the gene and the disease.
breast tumor (113 papers, 2006 to 2025). "TCGA data demonstrated that high HIF1α expression in breast tumors was associated with poor prognosis." (PMID 34595177, 2021). "Its family member, CITED4, has been analysed in breast tumours and was found to be associated with HIF1α expression and to be either lost or translocated into the cytoplasm during tumour progression." (PMID 19904269, 2009). "Since bone disseminated breast tumor cells can cause the formation of osteolytic lesions, we first assessed trabecular bone volume of tibiae from Hif1αf/f PyMT+ and Hif1α−/− PyMT+ mice by microcomputed tomography (microCT) as a readout of tumor-induced bone destruction." (PMID 34556788, 2021). "Of note, in ERα breast tumor patients, a hypoxia metagene signature together with upregulated HIF-1α expression were associated with lower response to endocrine treatment, corroborating the importance of ERα/HIF-1α crosstalk in the hormone response to treatment." (PMID 29996493, 2018). "For instance, the cytokine Oncostatin M, belonging to the Interleukin-6 (IL-6) family of cytokines, enhances HIF-1α protein stability and induces HIF-1α de novo synthesis via activation of mTORC2 in breast Tumor Associated macrophages (TAMs), leading to inflammatory reprograming." (PMID 29996493, 2018). "Expression data analysis using a metadata set composed of data from 1,881 breast tumors revealed that higher expression of HIF1A and a panel of hypoxia-responsive genes is associated with shorter DMFS interval of patients with basal-like tumors, but not other subtypes." (PMID 25069832, 2014). "As elevated levels of HIF-1α in breast tumors have been associated with metabolic changes in tumor cells, metastasis, and chemotherapy resistance, HIF-1α upregulation within the mammary microenvironment prior to tumor formation may contribute to the growth of more aggressive tumors." (PMID 37296891, 2023). "These orchestrated effects, including PD‐L1 expression, HIF1‐α‐induced vascularization, angiogenesis, and immunosuppression by protumoral macrophages in 4T1 breast tumors, further highlight the intricate metabolic and immunomodulatory dynamics within the TME." (PMID 38411356, 2024). "For example, HIF-2α in TAMs correlated with increased breast tumor microvessel density but so does whole tumor HIF-1α [PMID: 26079100] both of which are stabilized by hypoxia." (PMID 37124241, 2023). "A previous report demonstrated that Parkin targets HIF-1α for ubiquitination and induces degradation to inhibit breast tumor progression." (PMID 37185280, 2023). "HIF-1α levels were higher in BM-MSCs treated with CM from the breast tumor cell line MDA-MB-231 (MDA CM) than with CM from the control (CON CM)." (PMID 36230633, 2022). "We demonstrated that ROS and JAK/Stat3 synergistically lead to an increase in HIF-1α in BM-MSCs in vitro under normoxic conditions mimicking the breast tumor microenvironment." (PMID 36230633, 2022). "BM-MSCs were cultured in CM from breast tumor cells (MDA-MB-231 and MCF7) that simulate breast tumor conditions, and their HIF-1α expression was investigated." (PMID 36230633, 2022). "ROS and JAK/Stat3 cooperatively increased HIF-1α expression under normoxia in BM-MSCs in response to factors secreted from breast tumor cells." (PMID 36230633, 2022). "This is supported by the report that 4EBP1 promotes survival of breast tumors under hypoxia by stimulating the synthesis of pro-angiogenic factors, like HIF-1α and VEGF, to facilitate tumor angiogenesis in vivo." (PMID 35379801, 2022). "ROS and JAK/Stat3 cooperatively upregulate the expression of HIF-1α in bone marrow-derived mesenchymal stem cells under normoxic conditions in response to breast tumor cells." (PMID 36230633, 2022). "The ROS inhibitor NAC and the JAK inhibitor ruxolitinib suppressed the increase in HIF-1α protein in BM-MSCs in response to breast tumor-mimicking conditions." (PMID 36230633, 2022).
breast tumor (continued). "Surprisingly, combined targeting HIF-α mRNA and HIFAL lncRNA almost greatly abolished breast tumor growth in xenograft model and was much more effective than targeting HIF-1α mRNA or HIFAL lncRNA alone." (PMID 33637716, 2021). "It is well acknowledged that the transcription factor HIF-1α acts as a molecular sensor within the hypoxic breast tumor microenvironment toward aggressive cancer features." (PMID 32778144, 2020). "We corroborate these findings in clinical brain metastasis samples, in which we observe increased HIF1A and hypoxic signaling versus matched primary breast tumor samples." (PMID 33298946, 2020). "Taken together, the results of the present study demonstrate that LNT inhibits the growth of breast tumors in mice and the ability to metastasize to lung tissues, which is accompanied by the decline of HIF-1α in tumor tissues." (PMID 33245358, 2020). "Data extracted from the TCGA database also show a strong correlation between HIF-1α and miRNA-cluster expression in breast tumors." (PMID 32707933, 2020). "Increased nuclear HIF1A staining in matched brain versus breast tumors also shows a trend toward significant correlation with the number of brain metastases detected in each patient (r = 0.799; P = 0.057)." (PMID 33298946, 2020). "Canonical HIF1A target genes are significantly increased in brain metastases compared with primary breast tumors." (PMID 33298946, 2020). "In clinical specimens, brain metastases have elevated HIF1A protein expression, compared with matched primary breast tumors, and in patients with brain metastases, hypoxic signaling within CTCs predicts decreased overall survival." (PMID 33298946, 2020). "We also used human breast tumor tissues to test the correlation of miRNA with HIF-1α expression in tumors." (PMID 32707933, 2020). "HIF-1α expression is tightly regulated also within the breast tumor microenvironment, which is recognized as a critical player for disease development and progression." (PMID 29996493, 2018). "We further examined the function of BHLHE40 in breast tumor cells with elevated baseline activation of HIF1A and BHLHE40 using the tamoxifen-resistant (TR) and fulvestrant-resistant (FR) variants of MCF7 cells." (PMID 30285805, 2018). "Our previous study suggests that miR-153 suppresses breast tumor angiogenesis partially through targeting hypoxia-induced factor (HIF1α)." (PMID 29959560, 2018). "It’s worth mentioning that cytokines produced within the breast tumor stroma promote cancer cell growth also by engaging the HIF-1α/Notch signaling." (PMID 29996493, 2018). "HIF-1α is a key transcriptional factor for angiogenesis and metabolic reprogramming of tumor cells, and it is known that retinoic acid induces VEGF and HIF-1α in some tumors cells and promotes breast tumor progression depending on the cellular context." (PMID 30541574, 2018). "To directly demonstrate that the hypoxic microenvironment influences the tumor epigenetic landscape in vivo, we applied Pi-ATAC to EpCAM and HIF1α-stained cells in the MMTV-PyMT breast tumor model." (PMID 30389926, 2018). "In breast tumours, activated levels of the initiator of the coagulation cascade, phosphorylated tissue factor, were shown to be positively correlated with HIF1α expression in a recent study." (PMID 28302670, 2017). "Taken together these findings suggest that IGF1/IGF1R axis engages ERK1/2 and AKT signaling to trigger the activation of HIF-1α/GPER/VEGF transduction pathway in breast tumor microenvironment." (PMID 29212519, 2017). "Taken together, our results indicate that hypoxic induction of HIF-1α commonly decreases the levels of ER-α protein, which in turn reduce ER-α transcriptional activity in a variety of common breast tumor genetic backgrounds." (PMID 28320353, 2017). "Altogether, these results establish that HIF-1α/GPER signaling is required downstream of IGF1 for VEGF-mediated angiogenesis in the breast tumor microenvironment." (PMID 29212519, 2017).
breast tumor (continued). "EGFR promotes breast tumor growth and lung metastasis by HIF1α repression of miR-338-3p and subsequent activation of EYA2." (PMID 28703807, 2017). "SIRT3 is deleted in 40% of human breast tumours, and loss of SIRT3 increases reactive oxygen species production and HIF-1a stabilization." (PMID 27923043, 2016). "Taken together, these data indicate that DEK enhances breast tumor growth and angiogenesis in HIF-1α-dependent and -independent manners." (PMID 26988756, 2016). "In primary human breast tumours HIF1α was observed in 3 out of 4 tumours cultivated as slices with varying degrees of accumulation at the filter interface." (PMID 26647838, 2015). "Identifying potential targets for anti-HIF-1α treatment among breast tumors is an appealing goal, especially for tumors such as TNBC which, as of yet, have no available targeted therapy." (PMID 26046764, 2015). "In vivo experiments with breast tumour cell lines show amifostine administration results in HIF1α induction and in rats results in increased HIF1α accumulation in normal tissue." (PMID 25894815, 2015). "Analysis of previously published expression data revealed that higher expression of HIF1A and a panel of hypoxic genes is associated with a shorter interval of distant metastasis–free survival (DMFS) only in basal-like breast tumors." (PMID 25069832, 2014). "Within the basal-like breast tumors, we found a significant inverse correlation between the expression levels of miR-18a and HIF1A mRNA in all four data sets." (PMID 25069832, 2014). "The results of this study reveal a novel role for miR-18a in targeting HIF1A and repressing metastasis of basal-like breast tumors." (PMID 25069832, 2014). "The results of this study reveal a novel role for miR-18a in repressing metastasis of basal-like breast tumors by restricting HIF1A activity and regulating cell responses to hypoxia." (PMID 25069832, 2014). "In CD11b+ MDSC infiltrating 4T1 breast tumors (group 3), HIF1A, EGR1, NF-kappaB1 and c-jun are the transcription factors with the highest z-scores (HIF1A, EGR1, NF-kappaB1, c-jun)." (PMID 25294811, 2014). "The inverse correlation between miR-18a and HIF1A and hypoxia signature genes in basal-like breast tumors is significant in clinical samples and is consistent across multiple data sets." (PMID 25069832, 2014). "Taken together, these observations provide additional evidence in support of an essential role for miR-18a in regulating HIF1A activity in breast tumors." (PMID 25069832, 2014). "Our recent results demonstrating that HDAC inhibitors target both E-Cadherin and HIF-1α in breast tumors point to the promise of this type of therapeutic approach." (PMID 23530113, 2013). "CAIX is an HIF1α target and contributes to cancer aggressiveness in various biological contexts, such as the basal-like breast tumor subtype." (PMID 23372804, 2013). "The present results implicating HIF-1α and hypoxia signaling in mediating growth, metastasis and survival of breast tumor cells is consistent with HIF-1α as an important therapeutic target however thus far its exploitation has yet to be realized." (PMID 23530113, 2013). "On the other hand, the targeting of CAIX, which is induced by HIF-1α in breast tumour cells under hypoxia and involved in the pHi regulation also constitutes a promising therapeutic strategy." (PMID 23301832, 2013). "NMB-R (42 of 50 cases, 84%) and HIF-1α (37 of 50 cases, 74%) were highly expressed in the malignant epithelia, suggesting a correlation between NMB-R and HIF-1α expression in breast tumor tissues." (PMID 24349381, 2013). "Breast tumors expressing CD44+CD24-/low immunophenotype showed relationship with HIF-1α (p = 0.039) and negativity for HER-2 (p = 0.013)." (PMID 21824412, 2011). "HIF1A plays an essential role in cellular and systemic homeostatic response to hypoxia was recently found to regulate the metastasis of breast tumor to lung." (PMID 21806811, 2011).
breast tumor (continued). "HIF-1α was expressed in 93% of the breast tumours, and all samples showed some degree of GLUT-1 and CA-IX staining." (PMID 20932344, 2010). "In conclusion, our results suggest that breast tumor cells experience hypoxic conditions, as indicated by the expression of such markers as HIF-1α, Glut-1, leptin and ObR." (PMID 20569445, 2010). "A necrotic core developed in the breast tumour cell spheroids presumably due to the hypoxic central regions, with HIF1α staining evident surrounding the necrosis." (PMID 16404363, 2006). "However, when HIF-1α was knocked down, hirudin lost its inhibitory effects on breast tumor cell aggregation, adhesion and desmosome junction formation." (PMID 41381723, 2025). "We then investigated the expression levels of the HIF1A in breast tumor tissues." (PMID 40097917, 2025). "Additionally, protumoral macrophages promote PD‐L1 expression and HIF1‐α‐induced vascularization in 4T1 breast tumors, resulting in increased angiogenesis and immunosuppression." (PMID 38411356, 2024). "In addition, they described that HIF-1α plays a critical role in collagen biogenesis in breast tumors by upregulating the expression of P4HA1, P4HA2, PLOD1, and PLOD2 hydroxylases as well as the lysyl oxidase family members LOX, LOXL2, and LOXL4." (PMID 37686617, 2023). "HIF-1α ubiquitination and degradation via parkin abolished breast tumor metastasis." (PMID 36980235, 2023). "Parkin inhibits breast tumor progression through degradation of HIF-1a by inducing ubiquitination." (PMID 36831455, 2023). "Similarly, miR-20a and 20b are also differentially distributed within breast tumor mass, along with the opposite expression patterns of HIF1α and VEGFA in these tumors." (PMID 37583933, 2023). "Remarkably, the reprogramming of miRNAs transcriptional profile was accompanied by changes in the expression of key miRNA/mRNA coregulation networks, such as miR-935/HIF-1A, which correlated with the expression found in clinical breast tumors and predicted poor patient outcomes." (PMID 35626094, 2022). "Whether the increase in HIF-1α mRNA is due to increased transcription of HIF-1α in BM-MSCs in response to breast tumor-mimicking conditions or due to HIF-1α mRNA stabilization is not yet known." (PMID 36230633, 2022). "We also investigated whether the high VEGF expression in BM-MSCs is dependent on or independent of HIF-1α, as well as the mechanisms that increase HIF-1α expression in BM-MSCs in response to breast tumor cells." (PMID 36230633, 2022). "Our study demonstrated that NIR-PMCs could significantly improve the hypoxia status and inhibit HIF-1α and adenosine production in cancer cell spheroids and breast tumour." (PMID 35918337, 2022). "Furthermore, HIF-1α induced by in vitro normoxic conditions mimicking the breast tumor microenvironment promoted VEGF expression in BM-MSCs which, in turn, enhanced the angiogenic sprouting capacity of HUVECs." (PMID 36230633, 2022). "We recently reported that in a PyMT mouse model of breast cancer, breast tumors containing wild type and HIF-2α-deficient macrophages (containing only HIF-1α) had elevated numbers of tumor TEMs, increased hypoxia, and poor vessel perfusion that limited docetaxel delivery and efficacy." (PMID 35008355, 2021). "In a set of exploratory analyses, we described differences in HIF-1α expression between primary and paired recurrent breast tumors, and evaluated if conservation of HIF-1α expression between primary and recurrent tumors was also associated with late recurrence." (PMID 34736510, 2021). "In this regard, our previous studies have demonstrated that upon hypoxia and other stimulatory factors, the G protein estrogen receptor, namely GPER, may contribute to the action of HIF-1α toward breast tumor growth and angiogenesis." (PMID 32778144, 2020). "Likewise, hypoxia-activated HIF-1α plays a role in the tumor-related inflammation leading to worse clinical outcomes in diverse types of cancers including breast tumors." (PMID 32778144, 2020).
breast tumor (continued). "The results of the study indicated that SGHZF can inhibit breast tumour growth in mice and that the mechanism may be related to the inhibition of Akt and HIF-1α expression." (PMID 33414839, 2020). "Leptin, an adipokine, can de-stable HIF-1α and stimulate hypoxia condition in breast tumors." (PMID 31398937, 2019). "On the other hand, in the hypoxic breast tumor microenvironment, HIF-1α triggers Notch-3 up-regulation toward the decrease of IL-6 levels and the inhibition of the CSCs population, whereas the gamma secretase inhibitors MK-0752 and RO4929097 increase the CSCs population in an IL-6 dependent manner." (PMID 29996493, 2018). "This study suggests that EGFR- and HER2-mediated induction of HIF-1α expression may play a relevant role in breast tumor angiogenesis and progression." (PMID 29996493, 2018). "Together with our in vitro findings, these clinical data analyses support the hypothesis that hypoxia/HIF-1α drive CA in patient breast tumors and contribute to poor outcomes, such as distant metastasis." (PMID 28272508, 2017). "We hypothesize that inhibitors of HIF-1α or the proteasome might stabilize ER-α expression in breast tumors in vivo, and work in combination with endocrine therapies to reduce resistance." (PMID 28320353, 2017). "On the basis of the findings above that indicate that a functional interplay between HIF-1α and GPER regulates the expression of the key angiogenic mediator VEGF, we next evaluated the contribution of HIF-1α/GPER signaling to the stimulatory response induced by IGF1 in breast tumor microenvironment." (PMID 29212519, 2017). "In addition, a strong positive correlation between nuclear HIF-1α WI and CA was found in breast tumor samples (Spearman’s rho p = 0.722, p < 0.001)." (PMID 28272508, 2017). "However, escin Ia (2 mg/kg, 4 mg/kg) showed little effect on protein and mRNA expression of HIF-1α in breast tumors of mice." (PMID 27008697, 2016). "Indeed, when gene expression analysis was conducted on fresh surgical specimens, the HypoxyGluMet array revealed that breast tumors exhibited a 2.5-fold increase in expression of HIF-1α compared with benign tissues." (PMID 26316122, 2015). "Analysis of previously published data revealed that higher expression of HIF1A and a panel of hypoxic genes is associated with shorter DMFS interval in patients with basal-like breast tumors, and that, within this subtype, miR-18a expression is inversely correlated with hypoxic gene expression." (PMID 25069832, 2014). "Interestingly, a recent publication by Curran and Keely highlights the convergence of TGFβ and HIF1α signaling pathways as a key contributor to the cross-talk between breast tumor cells and stromal cells." (PMID 24618895, 2014). "In mammospheres exposed to the breast tumor fibroblasts supernatant, autocrine tumor necrosis factor-α signalling engenders the functional interplay between peroxisome proliferator activated receptor-α and hypoxia inducible factor-1α (PPARα/HIF1α)." (PMID 23372804, 2013). "In addition, we further demonstrated that antagomir-21 inhibits angiogenesis by suppressing the HIF-1α/VEGF/VEGFR2 signaling pathway in breast tumor." (PMID 23951172, 2013). "We believe that EGCG can block highly activated NFκB and HIF-1α pathways in breast tumor." (PMID 23638734, 2013). "Here we demonstrated that CD44+CD24-/low breast tumors show an association with HIF-1α status, but not with CAIX." (PMID 21824412, 2011). "There are evidence that hypoxia could drive the maintenance of CSC, via HIF-1α expression, but it still to be determined whether hypoxia markers are expressed in breast tumors presenting CD44+CD24-/low immunophenotype." (PMID 21824412, 2011). "The HER2 related tumors that are characterized by high levels of predicted hypoxia response display enhanced levels of hypoxia-related genes including HIF-1α, exhibit similar patterns of pathway activity and gene expression as compared to basal-like breast tumors." (PMID 21672245, 2011).